MFN2 (mitofusin 2)
Diseases named in the same sentence as MFN2 in open-access papers (continued):
Sharing a sentence is not in itself a finding about the gene and the disease.
heart disease (12 papers, 2012 to 2025). "Alternately, we reasoned that manifestation of a cardiac phenotype unique to mice carrying the MFN2 R400Q mutation would provide unbiased evidence linking it to in vivo heart disease." (PMID 37910431, 2023). "Thus, MFN2 Q400-induced dysfunction of either fusion or mitophagy could underlie its apparent over-representation in human heart disease." (PMID 37910431, 2023). "As a mitochondrial fusion protein, MFN2 participates in the process of heart disease by regulating proteolysis and inducing mitochondrial oxidative stress." (PMID 36760573, 2023). "To date, many studies have confirmed that the fusion and fission dynamins of cardiac mitochondria, in particular the GTPase dependent dynamins (DRP1, MFN1, MFN2, OPA1) are associated with the occurrence and development of various heart diseases." (PMID 34660720, 2021). "On the other hand, if our idea is correct that the dominant inhibitory effect of Mfn2 400Q relates to its disruption of both homotypic (i.e. Mfn2-Mfn2) and heterotypic (i.e. Mfn1-Mfn2) mitofusin interactions, then its pathological potential should be equally great in mammalian heart disease." (PMID 22957060, 2012). "In the human condition, however, loss-of-function Mfn2 mutations identified as causing neurodegenerative syndromes have not been associated with cardiac disease." (PMID 22957060, 2012). "Downregulation or post-translational modification of these fusion proteins have been confirmed as related to a variety of heart diseases, however, the specific mechanisms through which MFN1, MFN2, and OPA1 function in cardiomyocytes require further research." (PMID 34660720, 2021). "As mitochondrial fission and fusion are primarily regulated by mitochondrial dynamins in a GTPase-dependent manner, GTPase-dependent mitochondrial fusion (MFN1, MFN2, and OPA1) and fission (DRP1) proteins, which are abundant in the adult heart, can also be regulated in heart diseases." (PMID 34660720, 2021). "However, it is important to take into consideration the pleiotropic roles of the mitochondrial shaping proteins especially the fusion proteins, Mfn2 and OPA1, when targeting the mitochondrial shaping proteins as a treatment for cardiac disease." (PMID 28190190, 2017).
cardiovascular diseases (10 papers, 2016 to 2025). "Recent studies indicate that Mfn2 deficiency is involved in cardiovascular disease." (PMID 37627777, 2023). "Meantime, the interrelations study of c‐Myc and DNMT1 on the regulatory mechanisms of MFN2 will provide a therapeutic target for Hcy‐induced cardiovascular diseases." (PMID 31104361, 2019). "Our current knowledge points towards Mfn2 being involved in proliferative cardiovascular diseases, and suggests a possible role for Mfn2 in other proliferative disorders." (PMID 29068134, 2018). "Although H2S is known to regulate Mfn2, currently there are no data on the use of H2S donors specifically in the treatment of Mfn2-related cardiovascular diseases." (PMID 39334911, 2024). "Moreover, both OPA1 and Mfn2 were reported to be decreased regarding cardiovascular disease, but in our study, both biomarkers were not altered in the nontreated vitamin C groups." (PMID 34831251, 2021).
neurological disorders (8 papers, 2012 to 2024). "Mitofusion 2 (Mfn2) is one such protein that regulates mitochondrial fusion in which mutations lead to the neurological disease." (PMID 29391029, 2018). "In previous studies, MFN2 mutations have been linked to neurological disorders including CMT type 2 (CMT2)." (PMID 26956144, 2016). "In previous studies, MFN2 mutations have been linked to neurological disorders including CMT2 (named as CMT2A2, OMIM#609260)." (PMID 26956144, 2016). "Meanwhile, the fact that impaired MERCs are also implicated in several other neurological disorders, is also consistent with the notion that dysfunctional MERCs are also likely to be relevant to the disease pathology of MFN2-linked CMT2A." (PMID 35399520, 2022).
mitochondrial disease (6 papers, 2020 to 2024). "In addition to the two widely-studied mitochondrial proteins OPA1 and MFN2, mutations in SLC25A46 have also been identified as a pathogenic cause in a spectrum of neurological and mitochondrial diseases." (PMID 34945750, 2021). "In summary, combining evidence from different models, we have identified an essential role for MFN2 in neutrophil adhesion and migration, and determined the downstream mechanism, which provides insights and potential therapeutic strategies for inflammatory diseases and mitochondrial diseases." (PMID 32788232, 2020). "In addition, we reveal a previously unknown function of MFN2 in regulating the actin cytoskeleton, contributing to the understanding and management of patients with MFN2-related mitochondrial diseases." (PMID 32788232, 2020).
genetic disorder (4 papers, 2012 to 2025). "CMT2 is a highly heterogeneous genetic disorder but 4 genes are the most frequently involved : the GJB1 (connexin-32), MPZ (P0 or myelin protein-zero), MFN2 (mitofusin 2) and GDAP1 (ganglioside-induced differenciation-associated protein 1)." (PMID 24804794, 2014).
myopathy (4 papers, 2021 to 2025). A disease of the muscle in which the muscle fibers do not function properly. "We report an individual with a late-onset myopathy phenotype and a previously uncharacterized variant in the MFN2 gene." (PMID 40175090, 2025). "In summary, we observed elevated mtDNA-mediated TLR9/NF-κB and cGAS-STING inflammatory signalling in a patient harbouring the uncharacterized MFN2 Q367H variant who displayed late-onset myopathy as a standalone phenotype." (PMID 40175090, 2025). "With respect to how MFN2 dysfunction might cause myopathy, in the first report of an MFN2-specific mouse muscle KO, the authors argued that mtDNA depletion was likely a key contributory factor because of reduced oxidative phosphorylation." (PMID 40175090, 2025). "Future cases of myopathy associated with this variant in MFN2 may benefit from the inclusion of electron microscopic examination of muscle biopsy tissues." (PMID 40175090, 2025). "Overall, our findings are consistent with MFN2 dysfunction contributing to inflammation, which is a possible explanation for myopathy initially described in the proband." (PMID 40175090, 2025). "As elevated inflammation can cause myopathy, our findings linking the Q367H MFN2 variant with elevated TLR9 and cGAS-STING signalling can explain the patient’s myopathy." (PMID 40175090, 2025). "Characterization of the transdifferentiated patient myoblasts provides further evidence of MFN2 dysfunction and important insight into the muscle myopathy phenotype in the patient." (PMID 40175090, 2025). "Functional characterization of patient fibroblasts, transdifferentiated myoblasts, and a KO re-expression cell model reveals mtDNA-mediated inflammation likely explains the patient myopathy, thus expanding our understanding of the mechanisms by which MFN2 dysfunction contributes to pathology." (PMID 40175090, 2025). "Finally, the elevated levels of inflammation in patient-derived transdifferentiated myoblasts further support a novel disease pathomechanism for MFN2-mediated inflammation driving myopathy." (PMID 40175090, 2025). "Although MFN1 and OPA1 deficiency can cause inflammatory myopathy in mouse muscle KO models, the role of mtDNA-mediated inflammation in MFN2 pathology has not been fully explored." (PMID 40175090, 2025). "Gastrocnemius myoatrophy appeared to be a consequence of neuronal die-back rather than a primary myopathy as transmission electron microscopy showed normal myofilament architecture in the Mfn2 T105M KI mice, which was not changed by mitofusin activation." (PMID 39284622, 2024).
bacterial infection (3 papers, 2021 to 2022). "Recent studies have shown that the AMP-activated protein kinase energy sensor interacts directly with MFN2, inducing autophagy in response to energy stress, confirming that MFN2 is essential for immune system activation during bacterial infection." (PMID 36076909, 2022). "We found that myeloid cell-specific MFN2 is essential for antimicrobial and inflammatory responses in vitro and in vivo during intracellular bacterial infection." (PMID 33972668, 2021). "Overall, our findings demonstrate that MFN2 is a key coordinator of innate immune responses against intracellular bacterial infection through the maintenance of aerobic glycolysis and activation of xenophagy via HIF-1α." (PMID 33972668, 2021). "In this article, we review the role of MFN2 in the regulation of innate immune responses during viral and bacterial infections." (PMID 34482801, 2021). "We found that MFN2 plays a role in controlling excessive mitochondrial fragmentation during intracellular bacterial infection." (PMID 33972668, 2021). "Our data suggest two overarching considerations regarding the mechanisms by which MFN2 contributes to innate host defense through coordination of immunometabolism and xenophagy via HIF-1α during intracellular bacterial infection." (PMID 33972668, 2021). "Our findings reveal the mechanistic regulations by which MFN2 tailors the innate host defense through coordinated control of immunometabolism and xenophagy via HIF-1α during bacterial infection." (PMID 33972668, 2021). "Herein we show that mitofusin-2 (MFN2), a mitochondrial fusion protein, promotes innate host defense through the maintenance of aerobic glycolysis and xenophagy via hypoxia-inducible factor (HIF)-1α during intracellular bacterial infection." (PMID 33972668, 2021). "Here we report that MFN2 promoted macrophage inflammatory signaling through optimal induction of aerobic glycolysis via hypoxia-inducible factor (HIF)-1α, which is activated by mitochondrial respiratory chain complex I and ROS, triggered by bacterial infection." (PMID 33972668, 2021). "Although we did not analyze the differences in mitophagy flux between Mfn2 WT and Mfn2 CKO macrophages, our data strongly suggest that MFN2 does not affect mitophagy activity during intracellular bacterial infection." (PMID 33972668, 2021).
infectious disease (2 papers, 2021 to 2023). A disorder directly resulting from the presence and activity of a microbial, viral, or parasitic agent in humans. "Furthermore, the pathophysiological roles of MFN2 in human infectious diseases will need to be characterized in future clinical studies." (PMID 34482801, 2021).
inflammation (2 papers, 2022 to 2025). Aberrant reaction of the microcirculation characterized by movement of fluid and leukocytes from the blood into extravascular tissues. "However, Mfn2 silencing reversed the relief of Pue on periapical inflammation and bone destruction in PD mice (the PD + Pue + siMfn2 group vs. the PD + Pue + siMfn2 NC group)." (PMID 40312745, 2025). "Taken together, Pue treatment might relieve PD, such as alleviating periapical inflammation and bone destruction as well as enhancing osteogenic differentiation in periapical tissues, by enhancing mitochondrial autophagy via activating mitochondrial Mfn2." (PMID 40312745, 2025).
retinopathy (2 papers, 2020 to 2021). "Although the detailed mechanisms of action in the development of DR are still unknown, involvement of mitochondrial dysfunctions with ROS formation and a decrease of the mitochondrial fusion protein mitofusin 2 (Mfn2) have been found in experimental models of this retinopathy." (PMID 34222230, 2021). "Re-institution of good glycemia had no beneficial effect on hypermethylation of Mfn2 and Mlh1 and retinal function (electroretinogram), and the retinopathy continued to progress." (PMID 32313015, 2020).
disease of the peripheral nervous system (1 paper, 2023). "Although CMT is described as a disease of the peripheral nervous system, CNS involvement is reported in the literature in several CMT patients by variations in the MFN2, PMP22, GJB1, GDAP, MORC-2, NDRG1 and NEFL genes." (PMID 37238449, 2023).
reproductive diseases (1 paper, 2022). "However, the role of Mfn2, especially the upstream and downstream molecular mechanisms mediating the effects of Mfn2 on reproductive diseases has yet to be dissected; in particular, studies that specifically target the reproductive disorders caused by Mfn1 have yet to emerge." (PMID 35725948, 2022).
MFN2 also shares sentences with these, for which no sentence is quoted: cerebellar ataxia (5 papers); Huntington disease (5); acute myocardial infarction (3); hypertrophy (3); Parkinsonism (3); polycystic ovary syndrome (3); pulmonary hypertension (3); sensorineural hearing loss (3); dementia (2); hyperlipidemia (2); interstitial cystitis (2); liver (2); partial lipodystrophy (2); psychosis (2); acquired lipodystrophy (1); acute respiratory distress syndrome (1); acute-on-chronic liver failure (1); adenoma (1); adenovirus infection (1); anaplastic thyroid carcinoma (1); Arrhythmia (1); autosomal dominant disease (1); axonal hereditary motor and sensory neuropathy (1); Behr syndrome (1); benign tumors (1); Blindness (1); Brown-Vialetto-Van Laere syndrome (1); cardiac arrest (1); cerebrovascular diseases (1); cervical tumor (1).
A further 67 diseases each share a sentence with MFN2 in 1 paper.